BRCA2 (BRCA2 DNA repair associated)
Diseases named in the same sentence as BRCA2 in open-access papers (continued):
Sharing a sentence is not in itself a finding about the gene and the disease.
breast cancer (continued). "Between 25-40% of these cases involves the inheritance of one defective copy of either the BRCA1 gene or the BRCA2 gene which predisposes women in these families to a ~50-80% lifetime risk of developing breast cancer and to a lesser extent ovarian cancer." (PMID 20735817, 2010). "Germline mutations in either of the two predisposing genes, BRCA1 and BRCA2, account for a significant proportion of hereditary breast cancer." (PMID 20579331, 2010). "For example, the mutation BRCA2*6174delT is present in approximately 1% of Ashkenazi Jews, and is present at increased frequencies in early-onset Ashkenazi Jewish breast cancer cases and families." (PMID 20470408, 2010). "Using this combinatorial approach we were able to demonstrate a threefold enrichment of genes that contain SNPs associated with breast cancer risk for BRCA1 or BRCA2 mutation carriers." (PMID 21114847, 2010). "The mean age at diagnosis of breast cancer in BRCA1 mutation carriers was 42.4 years while in BRCA2 mutation carriers was 34.3 years." (PMID 20579331, 2010). "BRCA1 and BRCA2 mutations are found in a proportion of families with multiple early-onset breast cancers." (PMID 20807450, 2010). "To investigate the impact of BRCA1 and BRCA2 deficiency on chromosomal instability in breast epithelial cells, we performed aCGH on mammary tumors derived from our genetically engineered mouse (GEM) models for BRCA1- and BRCA2-associated breast cancer." (PMID 20735817, 2010). "The aim of this study was to establish and characterise a new human breast carcinoma xenograft obtained from a woman carrying a germline BRCA2 mutation." (PMID 20877358, 2010). "Women with mutations in the breast cancer genes BRCA1 or BRCA2 have an increased lifetime risk of developing breast, ovarian and other BRCA-associated cancers." (PMID 21637503, 2009). "Using Taqman Low Density Array technology, we investigated the BRCA2 loss of function role in sporadic breast cancers and the links existing with soy isoflavones on a panel of nuclear receptor expression." (PMID 19442290, 2009). "Germline mutations in the BRCA1 or BRCA2 genes significantly increase the risk of developing early-onset breast cancer." (PMID 19589159, 2009). "Mutations in the BRCA1 and BRCA2 tumour suppressor genes have been associated with the breast cancer risk among families with strong recurrence of the disease." (PMID 19232099, 2009). "Mutations in two major genes, BRCA1 and BRCA2, account for up to 30% of families with hereditary breast cancer." (PMID 19352458, 2009). "Genetic testing for mutations in BRCA1 and BRCA2 is available in Canada for women with a significant family history of breast cancer." (PMID 19088722, 2009). "The CHEK2*1100delC mutation confers a low risk of breast cancer in non-BRCA1/BRCA2 mutation carriers." (PMID 19656415, 2009). "Vast majority of studies has shown a highly increased risk of developing breast cancer in BRCA1 or BRCA2 mutation carriers with also a greater incidence of a second contra-lateral tumour." (PMID 19232099, 2009). "Women who carry mutations in the BRCA1 and BRCA2 genes have a substantially increased risk of developing breast cancer and ovarian cancers as compared with the general population." (PMID 19843326, 2009). "Examples of currently used genetic biomarkers are the breast cancer susceptibility gene 1 (BRCA1) or breast cancer susceptibility gene 2 (BRCA2)." (PMID 19128481, 2009). "Germline mutations in BRCA1 or BRCA2 genes have been demonstrated to increase the risk of developing breast cancer." (PMID 19232099, 2009).
breast cancer (continued). "Molecular screening for BRCA1 and BRCA2 mutations is now an established component of risk evaluation and management of familial breast cancer." (PMID 19298662, 2009). "For all of the descendants of this ancestor, we identified all individuals with diagnosis of a known BRCA2-associated cancer (breast cancer, prostate cancer, ovarian cancer, pancreatic cancer, and melanoma) using linked UCR data." (PMID 19476645, 2009). "BRCA2 is a high-risk breast cancer predisposition gene and is also known as FANCD1, responsible for causing FA-D1." (PMID 19127258, 2009). "Other breast cancer associated founder mutations (BRCA2, CHEK2, NBS1) were detected only in single patients." (PMID 19338682, 2009). "Germline mutations in the BRCA1 and BRCA2 genes account for a considerable fraction of familial predisposition to breast cancer." (PMID 19589159, 2009). "The association between high density and risk is also believed to be present in women who are already at an elevated risk of breast cancer as a result of carrying a mutation in the BRCA1 or BRCA2 genes." (PMID 19903338, 2009). "Breast cancer in men seems more frequently to be hormone receptor positive and the BRCA2 mutation confers a significant risk to men." (PMID 19584580, 2009). "BRCA1 mutations are associated with female breast and ovarian cancer, while BRCA2 mutations are rather associated with female and male breast cancer and to a lesser extent with ovarian cancer." (PMID 19352458, 2009). "Part of this familial clustering shows autosomal dominant inheritance with high penetrance due to mutations in the BRCA1 (MIM 113705) and BRCA2 (MIM 600185) breast cancer genes." (PMID 19619314, 2009). "A lower breast cancer-specific overall survival rate was observed in BRCA2 mutation carriers after the first two years from diagnosis." (PMID 19232099, 2009). "Unclassified variants (UVs) in the BRCA1/BRCA2 genes are a frequent problem in counseling breast cancer and/or ovarian cancer families." (PMID 19200354, 2009). "Female carriers of BRCA1 and BRCA2 mutations have an estimated 50–90% life-time risk to develop breast cancer, classifying both genes as high-risk susceptibility genes." (PMID 19607694, 2009). "Germline mutations in the BRCA1 and BRCA2 genes are identified in about one quarter of the families with breast cancer." (PMID 19607694, 2009). "5C perceived the action of Tamoxifen to reduce the risk of breast cancer for BRCA2 carriers as something that clinicians 'intuitively understand', and acknowledged that the lack of 'hard data' had 'never stopped anyone doing anything' (quotes 21 and 22)." (PMID 19409108, 2009). "Rare mutations in the coding sequence of BRCA1 and BRCA2 and a growing number of other genes involved in maintaining genomic stability have been shown to confer high to moderate risks of breast cancer." (PMID 19183483, 2009). "It has been estimated that the risk of developing breast cancer in those with BRCA1 or BRCA2 mutations is 45% to 65% respectively." (PMID 19144138, 2009). "Women who carry mutations in BRCA1 and BRCA2 have a substantially increased risk of developing breast cancer as compared with the general population." (PMID 19843326, 2009). "Women carrying BRCA2 mutations present a 25%–40% risk of breast cancer development and a 10%–20% risk of an ovarian cancer development." (PMID 19594871, 2009). "BRCA1 and BRCA2 can cause breast cancer in females, but only BRCA2 mutation confers a significant risk to men." (PMID 19584580, 2009). "The cumulative risk of breast carcinoma in carriers of BRCA1/BRCA2 mutations ranges from 45–84% by 70 years of age." (PMID 19724277, 2009). "CK14 was significantly associated with BRCA1 mutation but also with BRCA2 and non-BRCA1/BRCA2 groups of cancers, as compared with sporadic breast cancers." (PMID 18275599, 2008). "A total of 105 distinct BRCA1 variants (including 32 DDCVs) and 157 distinct BRCA2 variants (including 27 DDCVs) were identified in the 1,469 breast cancer patients." (PMID 18284688, 2008).
breast cancer (continued). "Breast cancer patients with a known deleterious mutation in BRCA1/BRCA2 are more likely to have a family history of breast cancer or ovarian cancer and an earlier age of diagnosis than noncarrier patients." (PMID 18284688, 2008). "Within the BRCA2 mutation-positive group, homozygous 72Pro carriers had a significantly older age of diagnosis of breast cancer compared to the mean age of diagnosis of either of the homozygous 72Arg (p = 0.041) and heterozygous (p = 0.018) carriers." (PMID 18402691, 2008). "Nonetheless, the potential modulation by CHEK2 of both BRCA1 and BRCA2 would point to an important function for this checkpoint kinase in the DNA damage repair pathways implicated in the development of breast cancer." (PMID 18797466, 2008). "Although the small sample size did not permit analysis of all possible haplotypes, we observed that BRCA2 mutation carriers harboring the Ins16minus-72Arg haplotype had a significantly younger mean age of diagnosis of breast cancer." (PMID 18402691, 2008). "For BRCA2 mutation carriers, the lifetime risk for breast cancer ranges from 45 to 85%, and between 11 and 27% for ovarian cancer." (PMID 18489799, 2008). "Given that only 2% to 3% of breast cancer patients have deleterious mutations in BRCA1 or BRCA2, understanding the clinical significance of this relatively large number of UVs is of great importance." (PMID 18284688, 2008). "Mutations in BRCA1 and BRCA2 account for a considerable proportion of these familial breast cancer cases, with the average cumulative risk in BRCA1 and BRCA2 mutation carriers by age 70 years estimated at 65% and 45%, respectively." (PMID 18497862, 2008). "To date, two main breast cancer susceptibility genes have been identified; BRCA1 and BRCA2 accounting for nearly half of high-incidence breast cancer families and an increased relative risk of breast cancer by 10- to 20- fold." (PMID 18637200, 2008). "The existence of a large number of breast cancer families who lack linkage to either BRCA1 or BRCA2 suggested that other breast cancer susceptibility genes remained undiscovered." (PMID 18706089, 2008). "To search for potential interactions between the products of these breast cancer susceptibility genes, we undertook systematic mapping of BRCA2 for potential phosphorylation sites by CHEK2." (PMID 18797466, 2008). "Expression profiles of short-term fibroblasts have previously been reported to separate carriers of a heterozygous mutation in the BRCA1 or BRCA2 genes from sporadic breast-cancer-affected controls." (PMID 18497862, 2008). "Within the BRCA2 mutation-positive group, carriers of the Ins16minus-72Arg haplotype had a significantly younger mean age of diagnosis of breast cancer (p = 0.009)." (PMID 18402691, 2008). "Many studies from the developed world report the prevalence of BRCA1 and BRCA2 mutations of breast cancer to vary from 1.8 – 13.1%." (PMID 18662409, 2008). "Families with inherited mutations in the BRCA2 gene give rise to a multi-site cancer phenotype, which includes besides breast cancer (in females and males), ovarian, colon, stomach, pancreatic, prostate and laryngeal cancer." (PMID 18783588, 2008). "BRCA1 and BRCA2 account for the majority of the known familial breast cancer risk, however, the impact of other cancer susceptibility genes largely remains to be elucidated." (PMID 18706089, 2008). "Another example of the commonly mutated tumour suppressor genes are BRCA1 and BRCA2, which are the only known high penetrance genes involved in breast cancer susceptibility." (PMID 19506729, 2008). "Inherited mutations in the genes BRCA1 and BRCA2 increase risk of breast cancer and contribute to a proportion of breast cancer families." (PMID 18497862, 2008). "The histopathological features of breast tumours from patients with BRCA1 and BRCA2 mutations differ from each other and from sporadic breast cancers." (PMID 18182994, 2008).
breast cancer (continued). "Here, we report the results of genetic testing for mutations in the BRCA1 or BRCA2 genes in a series of families with breast cancer in the multi-ethnic population (Malay, Chinese and Indian) of Malaysia." (PMID 18627636, 2008). "BRCA1 and BRCA2 mutations are highly penetrant with a lifetime risk of 46–87% and 26–84% respectively of developing breast cancer by the age of 70 years for mutation carriers." (PMID 18662409, 2008). "The BRCA2 999del5 mutation is much more frequent, accounting for around 40% of the hereditary cases and found in about 8% of unselected breast cancer cases and 0,4% of population based control." (PMID 18637200, 2008). "The BRCA2 DDCV carriers were also at a higher risk of having a first-degree family history of breast cancer or ovarian cancer compared with the normal/polymorphic BRCA2 carriers (odds ratio = 3.69) after adjusting for BRCA1 mutation status." (PMID 18284688, 2008). "In high-risk families, selected in a genetics service setting, women who test positive for the familial BRCA1/BRCA2 mutation are likely to have cumulative breast cancer risks in keeping with the estimates obtained originally from large families." (PMID 18513387, 2008). "Mutations in the high-risk breast cancer-susceptibility genes BRCA1 and BRCA2 account for approximately 15% of this excess familial risk." (PMID 18349832, 2008). "Overall, the BRCA mutation-negative cases had a significantly older mean age of diagnosis of breast cancer than each of the BRCA1 and BRCA2 mutation-positive groups (p = 0.02), as has been observed in previous studies of French Canadian breast cancer families." (PMID 18402691, 2008). "Several mutations in the PALB2 gene (partner and localizer of BRCA2) have been associated with an increased risk of breast cancer, including a founder mutation, 1592delT, reported in Finnish breast cancer families." (PMID 18637200, 2008). "There was a 10% higher cumulative incidence at most ages for breast cancer in those outside the BRCA2 OCCR, although lifetime risk was little different at 90% and statistical significance was not reached (p = 0.07)." (PMID 18513387, 2008). "Germ-line BRCA2 (MIM# 600185) mutations in female carriers confer a lifetime risk exceeding 80% for breast cancer and 20% for ovarian cancer, and a moderate increased risk of other cancer types." (PMID 18597679, 2008). "Major genetic factors associated with an increased risk of breast cancer for men include BRCA2 mutations, which are believed to account for the majority of inherited breast cancer in men, Klinefelter syndrome, and a family history." (PMID 18950495, 2008). "The cumulative risk for breast cancer for a woman carrying a BRCA1 or BRCA2 mutation is estimated to be as high as 85% by the age of 70 years and female carriers are also at a substantially increased risk of developing ovarian cancer." (PMID 18783588, 2008). "About 10% of breast cancer cases that are due to BRCA1 or BRCA2 mutations are considered familial, but the majority of breast cancer cases are sporadic." (PMID 19506729, 2008). "In contrast, the BRCA2 mutation carriers homozygous for the 72Pro allele had a significantly older age of diagnosis of breast cancer (p = 0.018)." (PMID 18402691, 2008). "The BRCA2 c.7007G>A mutation was found in 2 unrelated families: in an affected female with a severe family history of breast cancer, fulfilling criterion I, and in an affected male with a maternal aunt and cousin diagnosed with breast cancer." (PMID 18489799, 2008). "On the other hand, a recent study has found that Pro-A1 haplotype individuals present increased breast cancer risk, however, in BRCA2 mutation carriers." (PMID 18230179, 2008). "Within the BRCA2 mutation-positive group, homozygous Ins16 carriers had a significantly older age of diagnosis of breast cancer compared to the mean age of diagnosis of either of the homozygous Ins16minus (p = 0.042) or heterozygous (p = 0.046) carriers." (PMID 18402691, 2008).
breast cancer (continued). "Mutations are distributed throughout the entire coding region of BRCA2 and to date numerous deleterious mutations have been reported (Breast Cancer Information Core [BIC];)." (PMID 18597679, 2008). "The identification of a BRCA1 or BRCA2 mutation in familial breast cancer kindreds allows genetic testing of at risk relatives." (PMID 18513387, 2008). "In hereditary breast carcinoma, mutations in highly penetrant genes such as BRCA1 or BRCA2 confer a relatively high risk for developing breast carcinoma, though this risk accounts only for about 5 to 10% of all breast carcinoma cases." (PMID 18423013, 2008). "An analysis performed among carriers of BRCA1 and BRCA2 mutations, showed a greater incidence of breast cancer in younger birth-cohorts compared with relatives of these women belonging to older generations." (PMID 17488519, 2007). "In that study, first-degree male relatives of breast cancer patients carrying protein-truncating BRCA2 mutations had a RR of 4.8 (95%CI 3.3–6.3) for prostate cancer." (PMID 17700570, 2007). "By age 70 years, for BRCA1 carriers, breast cancer risk was 69% (SE 5%) and ovarian cancer risk was 46% (SE 6%), and for BRCA2 carriers, breast cancer risk was 74% (SE 8%) and ovarian cancer risk was 12% (7%)." (PMID 17213823, 2007). "Out of all breast cancers, 5 to 10% can be attributed to germline mutations in familial high-risk genes such as BRCA1 or BRCA2 that result in a lifetime breast cancer risk of about 45 to 65%." (PMID 17428320, 2007). "BRCA1 and BRCA2 gene carriers are at increased risk of developing contralateral breast cancer and appear, in the longer term, to have an increased rate of new primary tumours in the affected breast." (PMID 17697367, 2007). "For haplotype analysis, breast cancer families carrying the BRCA2-8765delAG mutation and originating from North-Sardinia (N = 3), Israel (N = 2), and French area of Canada (N = 2) were included into the study." (PMID 17640379, 2007). "For example, it has been demonstrated that about 15–30% of western breast cancer women aged less than 35 years are likely to have germ-line BRCA1 or BRCA2 mutations." (PMID 18053234, 2007). "The two major breast cancer susceptibility genes BRCA1 and BRCA2 are involved in 30% of hereditary breast cancer cases, but the discovery of additional breast cancer predisposition genes for the non-BRCA1/2 breast cancer families has so far been unsuccessful." (PMID 17760956, 2007). "We evaluated both the prevalence of the BRCA2-8765delAG variant in Sardinia and the putative existence of a common ancestral origin through a haplotype analysis of breast cancer family members carrying such a mutation." (PMID 17640379, 2007). "The unique haplotype common to all three breast cancer families from North Sardinia indicated the BRCA2-8765delAG as a founder mutation in this geographical area." (PMID 17640379, 2007). "Our group has also described the BRCA2-8765delAG variant as a founder mutation in about 12% breast cancer families originating from different villages of North Sardinia." (PMID 17640379, 2007). "Women carrying pathogenic gene mutations in either BRCA1 or BRCA2 are at significantly increased lifetime risk of up to 80% for developing breast cancer." (PMID 17324252, 2007). "In BRCA2 carriers, this study found that parity caused a borderline increase in risk for breast cancer before age 50 years (OR=1.17 for each pregnancy, 95% CI 1.01–1.36)." (PMID 17213823, 2007). "Classification of a hereditary family history of breast cancer in our sample primarily represented the presence of a BRCA1 mutation or a BRCA2 mutation." (PMID 17949495, 2007).